MNX1 (motor neuron and pancreas homeobox 1)
Diseases named in the same sentence as MNX1 in open-access papers (continued):
Sharing a sentence is not in itself a finding about the gene and the disease.
pancreatic adenocarcinoma (1 paper, 2022). "While its fold changes between normal and tumour samples were lower than MNX1 and MNX1-AS1, its expression levels were particularly high in gastro-intestinal tract and testicular tumours, with the highest negative fold change in pancreatic adenocarcinoma." (PMID 36429006, 2022).
polydactyly (1 paper, 2016). A disease characterized by the presence of polydactyly, including syndromic and non-syndromic forms. "Compared with genes detected in previous studies on chicken polydactyly, the MNX1/HLXB9 gene is a novel candidate gene associated with chicken polydactyly." (PMID 26859147, 2016).
respiratory failure (1 paper, 2024). The significant impairment of gas exchange within the lungs resulting in hypoxia, hypercarbia, or both, to the extent that organ tissue perfusion is severely compromised. "Mice lacking Mnx1 expression have defective motor neuron specification with axon pathfinding defects and die from respiratory failure after birth due to defective diaphragm innervation." (PMID 38689650, 2024).
testicular cancer (1 paper, 2022). A primary or metastatic malignant neoplasm that affects the testis. "While the association with GI organs may derive from the embryonic functions of MNX1, the expression of MNX1 and its antisenses in normal testis and testicular cancer does not seem to link with developmental activity." (PMID 36429006, 2022).
cancer (16 papers, 2014 to 2025). A tumor composed of atypical neoplastic, often pleomorphic cells that invade other tissues. "As a carcinogenic transcription factor, MNX1 (motor neuron and pancreas homeobox 1) enhances lipid synthesis and is associated with cancer aggressiveness, which is significantly increased in African American PCa." (PMID 40271194, 2025). "Additional studies revealed that MNX1 expression is strongly upregulated in different cancers, including breast 7, colon 8, prostate 5, and liver cancers." (PMID 37779874, 2023). "Related reports on MNX1 in cancer revealed that it is involved in promoting the proliferation of squamous cervical cancer by regulating cyclin E." (PMID 38203393, 2023). "lncRNAs are highly sensitive regulators of cancer growth, and MNX1′s expression has been found to be upregulated in not only BC, but also in all other cancers, although its exact contribution to tumorigenesis is uncertain." (PMID 35804819, 2022). "Motor neuron and pancreas homeobox 1 (MNX1) is a development-related genes and has been found to be highly expressed in several cancers." (PMID 32850410, 2020). "MNX1 has been implicated in the development of both solid and hematological malignancies, although more investigations of the underlying mechanisms are needed to fully understand the role of MNX1 in cancer biology." (PMID 30368216, 2018). "Through scratch wound assays, we noted that MNX1 overexpression promoted cancer cell migration." (PMID 37779874, 2023). "First, MTT assays showed that MNX1 knockdown inhibited cancer cell growth." (PMID 37779874, 2023). "Previous studies have also shown that MNX1 plays a role in several cancers." (PMID 30368216, 2018). "All these lines of evidence suggested that MNX1 is oncogenic in multiple cancer types." (PMID 30368216, 2018). "We hope these findings will draw more attention to MNX1 in future cancer studies." (PMID 30368216, 2018). "MNX1 protein has been proven to be an important regulator of many processes relevant to cancer." (PMID 30012177, 2018). "Moreover, one research illustrates that upregulated MNX1 has been discovered in prostate cancer cells, which might be an innovative biomarker of this cancer." (PMID 32850524, 2020). "Interestingly, several studies have revealed that MNX1 is upregulated in some solid human cancers." (PMID 30012177, 2018). "MNX1 is a member of the homeobox gene (HOX) family, and several homeobox genes are involved in the development of various malignant tumours." (PMID 37779874, 2023).
tumor (16 papers, 2018 to 2025). "MNX1 knockout activates cytotoxic T cell-mediated anti-tumor immunity and sensitizes tumors to CTLA-4 blockade." (PMID 41346602, 2025). "Previously, we demonstrated in an AML PDX mouse model with del(7q) and MNX1 expression that shRNA-mediated knockdown of MNX1 reduces the tumor load of AML PDX cells in vivo." (PMID 40659989, 2025). "In vivo tumorigenesis experiments in animals should be included in future experimental plans to observe the changes in tumor size after MNX1 overexpression and knockdown." (PMID 38203393, 2023). "The tumour weight and volume in the shRNA-E2F4 group were the lowest, whereas the continuous delivery of MNX1 overexpressed plasmids increased the tumour weight and volume." (PMID 37779874, 2023). "The tumour weight and volume in the shRNA-E2F4 group were the lowest, whereas the continuous delivery of overexpressed MNX1 plasmids increased the tumour weight and volume." (PMID 37779874, 2023). "Both in HeLa and Siha cells, knockdown of MNX1 upregulated the expression of p21cip1, which has been confirmed as a tumor suppressor gene in multiple cancers." (PMID 32850410, 2020). "Results showed that knockdown of MNX1 inhibited tumor growth (measured by tumor weight and volume) in vivo." (PMID 32850410, 2020). "The expression of MNX1 was elevated in patients with larger tumor size and more lymph node metastasis." (PMID 30368216, 2018). "The MNX1-overexpressing group had prominently increased tumor growth, whereas it was obviously suppressed in the MNX1 knockdown group, both as compared with the vector group." (PMID 30012177, 2018). "Ferguson, Gautrey and Strathdee had previously attributed MNX1 activity in haematopoietic cells to epigenetic dysregulation, and suggested that MNX1 could act as both tumour-suppressor and oncogene depending on methylation status." (PMID 36622782, 2023). "TCGA database analysis revealed that MNX1 expression was significantly higher compared with that in normal tissue in the pathological and clinical tumor stages (T stage), whereas PNMT expression was not significantly different in the pathological and T stages compared with that of normal tissue." (PMID 38203393, 2023). "There was a correlation between the expression level of MNX1 and tumor size (p < 0.0001)." (PMID 38203393, 2023). "Moreover, ectopic expression of MNX1 promoted tumor growth and altered the expression of p21cip1 and ki-67 in vivo." (PMID 32850410, 2020). "Moreover, MNX1 staining scores were linked to higher pathological grade (level II vs. III, p = 0.02) and larger tumor maximum diameter (d < 3 vs. ≥3 cm, p < 0.0001)." (PMID 32850410, 2020). "In summary, our study suggests that MNX1 may act as a tumor promoter in BC and that it may be involved in BC development through HER2-associated pathways or by regulating the cell cycle." (PMID 30368216, 2018). "Moreover, patients with advanced tumor (T) and lymph node (N) stages tend to have an increased MNX1 level." (PMID 30368216, 2018). "Taken together, MNX1 overexpression may play an important role in tumor development." (PMID 30012177, 2018). "In conclusion, our study suggests that MNX1 may act as a tumor promoter in BC." (PMID 30368216, 2018). "Meanwhile, MNX1 and E2F4 effects on cell migration, invasion and tumour growth were examined through in vivo and in vitro assays." (PMID 37779874, 2023). "Wang et al146 identified a putative tumor suppressor in AA men, RGS12, that influences apoptosis by reducing MNX1 and AKT levels." (PMID 33599076, 2021). "MNX1-overexpressing, MNX1 knockdown, or vector cells were subcutaneously injected into BALB/c-nu mice, and the tumor growth was measured." (PMID 30012177, 2018). "For CNS HGNET-BCOR detection, three probes for SHISA8, MNX1 and MMP15 showed diagnostic usefulness regardless of tumor location." (PMID 32650833, 2020).
tumor (continued). "Other genes such as KL, MNX1, HMCN1 and ADCY10 suggest that anoikis resistance is not restricted to survival pathways but also extends to metabolic and proliferative mechanisms that drive both tumour aggressiveness and treatment resistance." (PMID 40830065, 2025).
hematological malignancies (2 papers, 2018 to 2019). "In this study, we analyzed the nuclear repositioning of HLXB9 (also called MNX1), mapping at 7q36.3, in patients with hematological disorders carrying interstitial deletions of 7q of various extents, with a distal breakpoint in 7q36." (PMID 31027247, 2019).
genetic disease (1 paper, 2024). "Since MNX1 acts as a transcriptional repressor, loss of MNX1 activity in ALS motor neurons could have a transcriptional derepression effect, a common feature of genetic disease, which may account for increased expression of some DEGs in this study." (PMID 38689650, 2024).
hematological cancers (1 paper, 2012). "MNX1 function in immune cells and GBM biology has not been demonstrated yet but it has recently been described as a transcriptional factor implicated in the development of both solid and hematological cancers." (PMID 22980038, 2012).
neurological disorders (1 paper, 2017). "In this cohort, seven genes have already been associated with neurological disorders (MNX1, NINJ1, PER2, PHF20, PRSS56, RPH3A, and SBF1) in MalaCards and OMIM." (PMID 28769055, 2017).
MNX1 also shares sentences with these, for which no sentence is quoted: sacral agenesis (5 papers); lymph node metastasis (3); acute leukemia (2); acute lymphoblastic leukemia (2); infection (2); motor neuron disease (2); neuroblastoma (2); amyotrophic lateral sclerosis (1); breast tumors (1); caudal regression syndrome (1); COVID-19 (1); embryonal carcinoma (1); enterocolitis (1); holoprosencephaly (1); imperforate anus (1); invasive ductal carcinoma (1); lung adenocarcinoma (1); lymphopenia (1); medulloblastoma (1); myeloid leukemia (1); nail-patella syndrome (1); necrotizing enterocolitis (1); neuromuscular disease (1); neuropathy (1); sirenomelia (1); squamous cervical cancer (1); stomach cancer (1); uterine fibroids (1).